LRP5 (LDL receptor related protein 5)
Diseases named in the same sentence as LRP5 in open-access papers (continued):
Sharing a sentence is not in itself a finding about the gene and the disease.
breast cancer (continued). "We previously evaluated the role of Lrp5 and Lrp6 in a mammary tumor model in which the ectopic expression of Wnt1 under the control of the MMTV promoter (MMTV-Wnt1) causes the rapid onset of mammary tumors." (PMID 40932232, 2025). "In Ren's paper 24, knocking down LRP5 or LRP6 promoted lung metastasis of breast cancer cells in a nude mouse model." (PMID 38706907, 2024). "Recently, it has been shown that Dickkopf-Related Protein 1 (Dkk-1) secreted by the breast cancer cells circulates to BM/bones where it attracts OCPs to form a PMN by suppressing the LRP5–ß-catenin–Rnasek axis." (PMID 36890825, 2023). "Second, the incubation of freshly isolated breast-cancer-tissue fragments with Lrp5 CM and BML CM significantly reduced the size of tumor fragments in 4 days." (PMID 34976221, 2022). "We next employed a pair of mouse models and evaluated the effect of the daily systemic administration of Lrp5 CM on mammary tumors and tumor-invaded tibiae in female mice." (PMID 34976221, 2022). "In the mouse model of mammary tumors, the daily intravenous injection of Lrp5 CM from the tail vein for 2 weeks significantly reduced the size and weight of mammary tumors." (PMID 34976221, 2022). "In our previous study 34, a high dose of OPN in osteocytes, which were converted to iTSCs by the overexpression of Lrp5, inhibited tumorigenic genes such as TGFβ and Snail in breast cancer cells." (PMID 34976221, 2022). "The growth of breast cancer cells and tissues was inhibited by Lrp5-overexpressing CM (Lrp5 CM), which suppressed mammary tumors and tumor-driven bone destruction in a mouse model." (PMID 34976221, 2022). "We first examined the effect of Lrp5-overexpressing osteocytes in the tumorigenic behaviors of EO771 mammary tumor cells, using MLO-A5 osteocytes." (PMID 33802279, 2021). "BML284-treated macrophage-derived CM also downregulated Lrp5, Runx2, and TGFβ, and it reduced the size of human breast-cancer-tissue fragments (ER-/PR+/HER2+) ex vivo in 3 days." (PMID 34830748, 2021). "In a mouse model of mammary tumors and tibial osteolysis using C57BL/6 female mice, the co-injection of osteocytes to the mammary fat pad significantly reduced the size of mammary tumors and the anti-tumor effect was strengthened by the overexpression of Lrp5." (PMID 33802279, 2021). "Taken together, these results indicated that Lrp5-overexpressing mouse and human osteocytes acted as tumor suppressors not only in breast cancer cells but also in prostate cancer cells." (PMID 34230453, 2021). "This study showed that LRP5/6 downregulation is crucial for metastasis in mouse breast cancer models, suggesting that the binding of LRP5/6 to FZD inhibits the FZD-regulated non-canonical pathway and its further tumor metastasis." (PMID 31382613, 2019). "Low expression of LRP6 in ER+ve tumours was predictive of early recurrence, whilst low levels of LRP5 was predictive of early recurrence in ER-ve breast cancer." (PMID 23861811, 2013). "LRP5 was the only gene that was predictive in ER-ve breast cancer where low levels predict early recurrence." (PMID 23861811, 2013). "Mounting evidence suggests that Wnt induces mammary tumor formation from stem or progenitor cells via LRP5/6-mediated activation of ß-catenin and mTOR pathways." (PMID 24392029, 2013). "In vivo, systemic administration of LRP5-overexpressing osteocyte-derived conditioned medium reduced mammary tumor burden and mitigated osteolytic bone destruction in tibial metastasis, whereas genetic disruption of LIMA1 in osteocytes or MYO5B in tumor cells abrogated these protective effects." (PMID 41596426, 2026). "LRP5 appears to convert a tumor-driven vicious cycle into a bone-protective positive feedback loop, underscoring the therapeutic potential of targeting osteocytes in breast cancer and its bone metastases." (PMID 41596426, 2026).
breast cancer (continued). "In syngeneic mouse models of mammary tumors and bone metastasis, systemic administration of LRP5-overexpressing osteocyte-derived CM reduced tumor burden and osteolytic bone destruction, whereas genetic knockdown of LIMA1 in osteocytes or MYO5B in tumor cells abrogated these protective effects." (PMID 41596426, 2026). "Osteocyte-specific LRP5 overexpression endows osteocytes with tumor-suppressive properties, resulting in the secretion of conditioned medium (CM) enriched in factors that inhibit breast cancer cell proliferation and metastasis." (PMID 41596426, 2026). "Here, we show that conditioned medium from LRP5-overexpressing MLO-A5 osteocytes markedly inhibits EO771 breast cancer cell proliferation, migration, and invasion, and alters the expression of key tumor-related proteins—effects that are mediated by upregulation of LIMA1." (PMID 41596426, 2026). "Clinical data supports that the reduction of A. muciniphila and butyrate levels exhibited correlation among tumoral LRP5/β-catenin expression, anxiety and poor prognosis, indicating a promising role of microbial therapy in stress-related breast cancer for both treating and diagnosing breast cancer." (PMID 40038255, 2025). "Moreover, the butyrate suppression of LRP5 inhibits β-catenin expression, thus reducing breast cancer stemness." (PMID 40038255, 2025). "Our previous study has found that CUMS could enhance breast cancer stemness by activating GRP78/LRP5/β-catenin signaling pathway, which was also mediated by increased cortisol." (PMID 37210553, 2023). "Besides EO771 cells, Lrp5 CM reduced the tumor-invaded area by GFP-labeled MDA-MB-231 breast cancer cells that were inoculated in the tibia of NSG mice." (PMID 34976221, 2022). "Lrp5 CM converted a vicious cycle into a bone-protective beneficial loop, indicating the possibility of developing a unique secretome-based therapeutic strategy for breast cancer and bone metastasis." (PMID 34976221, 2022). "The basally restricted expression pattern of LRP5/6 may also provide a partial explanation for the observation that nucleocytoplasmic ß-catenin accumulation is selectively enriched in basal-like breast cancers." (PMID 22457761, 2012). "There are data to suggest that gain of function of Lrp5 or -6 is important to breast cancer." (PMID 19672307, 2009). "However, our results suggest that Lrp5 plays a pivotal role over Lrp6 in transmitting oncogenic Wnt signals in the MMTV-Wnt1 mammary tumor model." (PMID 19503830, 2009). "We therefore investigated the effects of LRP5-overexpressing osteocyte-derived CM on the expression of proteins associated with tumor progression (e.g., MMP9, Snail, cleaved caspase-3, IL-6, TGF-β1) and on breast cancer cell proliferation, migration, and invasion of tumor cells." (PMID 41596426, 2026). "However, the role of LRP5 demonstrates some discrepancies in breast cancer." (PMID 34997691, 2022). "LRP5 antibody therapy may have a significant role in the treatment of breast cancer." (PMID 19158955, 2009). "In mouse models, LRP5-overexpressing osteocyte-derived CM, acting through the LIMA1–MYO5B axis, inhibited mammary tumor growth and tibial osteolysis." (PMID 41596426, 2026). "Consistently, tumors from breast cancer patients with low butyric acid displayed lower ZFP36 mRNA and higher LRP5/NANOG/SOX2/Ki67 mRNA compared with patients with high butyric acid." (PMID 40038255, 2025). "Ren 24 has shown that in breast cancer, knockdown of LRP5 or LRP6 suppresses the Wnt signaling, but it increases lung metastasis in breast cancer cells in nude mice." (PMID 38706907, 2024). "We observed that the overexpression of Lrp5 in osteoblasts elevated the level of OPN, but Lrp5 CM reduced OPN in EO771 mammary tumor cells." (PMID 34976221, 2022). "More importantly, SNS inhibited breast cancer stemness by interrupting the interaction between GRP78 and LRP5 induced by chronic psychological stress." (PMID 34912211, 2021).
breast cancer (continued). "Lrp5-overexpressing osteocyte-derived conditioned medium (CM) also inhibited EdU-based proliferation and scratch-based migration of MDA-MB-231 breast cancer cells and EO771 mammary tumor cells." (PMID 33450808, 2021). "This phenomenon was particularly pronounced in breast cancer patient-derived xenograft (PDX) models, in which alterations of LRP5 were observed in more than 50% of cases, versus less than 7% of cases for LRP6." (PMID 29854300, 2018). "As LRP5 and LRP6 are coreceptors, we analyzed the expression of these two receptors in breast cancers and the effects of their depletion on the survival of breast cancer cells." (PMID 29854300, 2018). "We, therefore, analyzed the expression of both LRP5 and LRP6 in our set of breast cancer biopsy specimens." (PMID 29854300, 2018). "Mesoderm development (Mesd), which binds directly to mature LRP5 and LRP6 on the cell surface and inhibits Wnt3a-induced Wnt signaling, decreases the growth of breast cancer tumors in vivo." (PMID 29854300, 2018). "Together, these results indicate that both LRP5 and LRP6 are overexpressed in TNBC relative to other breast cancer subtypes." (PMID 29854300, 2018). "LRP5 DNA copy number (CN) in TNBC was higher than that in luminal A tumors only, but LRP6 DNA CN was higher in TNBC than in the other breast cancer subtypes." (PMID 29854300, 2018). "An aberrant splicing of LRP5, which removes the coding region of LRP5 that interacts with the extracellular antagonist DKK1, has been reported in human breast cancer." (PMID 27420097, 2016). "It is likewise reported that prostate and breast cancer cells produce DKK-138, 39 which, like sclerostin, inhibits Lrp5 (activator of the Wnt/ß-catenin pathway)." (PMID 27666393, 2016). "In the clinic, fecal A. muciniphila and serum butyrate are inversely correlated with tumoral LRP5/β-catenin expression and negative mood in breast cancer patients, conferring a better cancer prognosis." (PMID 40038255, 2025). "Clinically, fecal A. muciniphila and serum butyrate were inversely correlated with tumoral LRP5/β-catenin expression, poor prognosis and negative mood in breast cancer patients." (PMID 40038255, 2025). "In addition, HADS scores were negatively correlated with ZFP36 expression and positively related with LRP5, β-catenin and NANOG expression in cohort 1 breast cancer patients." (PMID 40038255, 2025). "The result revealed that the mammary tumor can be suppressed remotely by mechanical stimulation to the knee both in wild-type and knockout mice independent of osteocytic Lrp5." (PMID 33450808, 2021). "We analyzed expression of the WNT coreceptors LRP5 and LRP6 in human breast cancer samples." (PMID 29854300, 2018). "Given the stronger expression of the LRP5 and LRP6 coreceptors in TNBC than in other breast cancer subtypes, we then investigated the effects of knocking down LRP5 or LRP6 expression on cell viability in HCC38 and MDA-MB-468 TNBC cells, which have high levels of both LRP5 and LRP6." (PMID 29854300, 2018). "Deletion of Lrp5 in tumor cells reduced mammary tumor growth, but deletion of Lrp6 did not." (PMID 34230453, 2021). "In conclusion, our study revealed that chronic psychological stress could promote breast cancer stemness via activating GRP78-mediated CSCs, and SNS was capable of inhibiting breast cancer stemness and metastasis via interrupting the GRP78/LRP5 stem signaling under CUMS stimulation." (PMID 34912211, 2021). "Furthermore, internally truncated form of LRP5 (LRP5Delta) has recently been reported to be resistant to DKK1 inhibition and thus contributes to the activation of Wnt/β-catenin signaling in parathyroid and breast cancer." (PMID 22570728, 2012). "Interestingly, we also found a correlation between Lrp5 expression and basal-like breast cancer (p = 4.6×10–3, p = 3.7×10–3) (data not shown)." (PMID 19503830, 2009).
breast cancer (continued). "Hence, therapeutic interventions targeting LRP5 and/or LRP6 could be useful in treating some types of breast cancer, particularly the basal-like class for which few, if any, effective treatments exist." (PMID 19503830, 2009). "Indeed, mice lacking LRP5 form Wnt1-induced mammary tumors much later than wild-type mice." (PMID 29854300, 2018). "TM40D-MB breast cells which are highly metastatic to bone have higher mRNA levels of LRP5, LRP6 and β-catenin, as compared to TM40D cells, which are breast cancer cells that are non-bone metastatic." (PMID 31382613, 2019). "Interestingly, expression of LRP6, but not LRP5, has been shown to define a new class of breast cancer subtypes, as LRP6 is overexpressed in 20–36% of breast carcinomas." (PMID 31412666, 2019). "Furthermore, an anti-LRP5 antibody attenuated β-catenin activity, inhibited cell growth, and induced apoptosis in LRP5Δ-positive MCF7 and T-47D breast cancer cells, but not in control cells." (PMID 19158955, 2009).
diabetes (17 papers, 2011 to 2025). "The low-density lipoprotein receptor-related protein 5 (LRP5) and its inhibitor sclerostin, are key components of bone metabolism and potential contributors to type 2 diabetes mellitus susceptibility." (PMID 36947076, 2023). "Since then, it has been an important concept in the study of the insulin dependent diabetes mellitus (IDDM) whereby LRP5 expression was suggested to be associated with susceptibility to diabetes." (PMID 31031810, 2019). "The present study has investigated the association between low-density lipoprotein receptor-related protein 5 (LRP5) 4037C>T polymorphism and type 1 diabetes mellitus (T1DM) susceptibility in a Brazilian population." (PMID 30304114, 2018). "This region is linked to type 1 diabetes mellitus, whereas single nucleotide polymorphisms in WNT5b and LRP5 genes may contribute to susceptibility to type 2 diabetes mellitus (T2DM) and obesity." (PMID 36947076, 2023). "Interestingly, LRP5 was found to be associated not only with bone physiology but also with metabolic alterations, showing in a mouse model of diabetes that a gain-of-function Lrp5 mutation improved bone quality and delayed hyperglycemia." (PMID 35742976, 2022). "This structural and metabolic role of LRP5 presents it as a potential therapeutic target for kidney diseases, especially in individuals with diabetes with permanent renal tubular damage." (PMID 40940800, 2025). "On the other hand, mRNA expressions of DKK1, BMP-2, OSN, RUNX2, and LRP5, which decrease with diabetes in bone tissue, increase significantly with MF administration." (PMID 39202505, 2024). "Lin and colleagues showed that reduced expression of the endogenous inhibitor, DKK-1, which binds Wnt co-receptors LRP5/6, decreased diabetes-induced glomerular injury preventing hyperglycaemia-induced mesangial cell dysfunction." (PMID 21876774, 2011). "The WNT pathway is involved in glucose homeostasis, and mutations in LRP5, the receptor that mediates WNT signaling, may lead to the development of diabetes." (PMID 41007744, 2025). "Recently, semaglutide, a GLP1 receptor agonist frequently used in diabetes, has shown promising effects in the osteogenic differentiation of bone marrow stem cells via Wnt/LRP5/β-catenin signaling pathway activation in in vitro studies, and there is a need for in vivo studies to confirm this effect." (PMID 40940800, 2025). "We assume that this polarized distribution of LRP5 may play a role in reabsorbing glucose by renal tubules in response to diabetes, a property of LRP5 which has been demonstrated in mammary epithelial cells." (PMID 32345960, 2020). "The present study investigated pro-fibrotic effect of LRP5 in CKD models such as diabetes and UUO, and identified a new role of LRP5 in regulating the TGF-β/Smad signaling pathway to promote renal fibrosis." (PMID 32345960, 2020). "Staining of LRP5 confirmed the abundant distribution of LRP5 in the renal tubules of non-diabetic mice, and revealed that the diabetes-induced increases of LRP5 predominantly occurred in the renal tubules of Akita, db/db, and OVE26 (type 1 diabetes) mice." (PMID 32345960, 2020). "Furthermore, LRP5 is known to act as a protective factor for type-2 diabetes mellitus (T2DM), promoting insulin signaling in addition to increasing insulin production and lowering blood glucose, and the expression of LRP5 is critical for bone formation, especially osteoblasts." (PMID 38302983, 2024). "Notably, diabetes-induced LRP5 was predominantly located on the apical membrane and microvilli of renal tubules, although no obvious polarized distribution of LRP5 was detected in those of non-diabetic kidneys." (PMID 32345960, 2020).